MC4R (melanocortin 4 receptor)
Diseases named in the same sentence as MC4R in open-access papers (continued):
Sharing a sentence is not in itself a finding about the gene and the disease.
Anxiety (continued). "We evaluated for any potential behavioral side effects such as anxiety-like behavior or repetitive behaviors with MT-II in the normal C57BL/6J mice given the known role of acute MC4R stimulation in increasing stress behaviors in rodents." (PMID 30629642, 2019). "While previous investigators studied MC4R agonist effects on anxiety-like behavior following induced stress of restraints or forced swimming, we were interested in anxiety-like behavior without incurring psychological stress." (PMID 30629642, 2019). "This study reveals a novel mechanism by which ACTH mitigates anxiety-like behaviors and normalizes key astrocyte markers, including glial fibrillary acidic protein and aquaporin-4, following early-life seizures (ELS) in a melanocortin 4 receptor (MC4R)-dependent manner." (PMID 40015967, 2025). "The interaction of depression and anxiety with MC4R rs17782313 was not significant (p ˃ 0.05)." (PMID 36123585, 2022). "Also, previous reports have shown that acute treatment with MC4R agonists results in increased repetitive behavior and increased anxiety-like behavior in both the presence and absence of psychological stress." (PMID 30629642, 2019). "In line with that, the existence of a correlation between the total number of MC4R per hippocampal section and CDOA in our study could explain anxiety-like behavioral manifestations of administered AASs, as well as the elevation in number of MC4R positive cells." (PMID 30863280, 2019). "However, in MC4R KO mice, ACTH treatment did not ameliorate anxiety, showing that the anxiolytic effects of ACTH are mediated through MC4R signaling pathways." (PMID 40015967, 2025).
Hyperglycemia (26 papers, 2009 to 2025). An increased concentration of glucose in the blood. "In contrast, in ob/ob mice, loss of hepatic FASN resulted in marked exacerbation of fed hyperglycemia despite a greater suppression of gluconeogenesis compared with that apparent in Mc4r-KO mice." (PMID 37681411, 2023). "Our results showed that 62.5% of MC4R neurons in the DMH neurons are relevant to hyperglycemia due to their suppressed neural activity associated with high glucose levels." (PMID 37043384, 2023). "In ob/ob mice, hepatic FASN deficiency ameliorated hepatic steatosis and improved glucose tolerance to a greater extent than in Mc4r-KO mice, but it exacerbated fed hyperglycemia and liver dysfunction." (PMID 37681411, 2023). "Moreover, whereas hepatic FASN ablation ameliorated hepatic steatosis and improved glucose tolerance in NCD-fed ob/ob mice to a greater extent than in Mc4r-KO mice, it also exacerbated both hyperglycemia in the fed state and liver dysfunction." (PMID 37681411, 2023). "Potential ClpB targets, relevant to its anti-hyperglycemic effect, may include MC4R expressing cholinergic parasympathetic neurons, in which activation by MC ligands attenuates hyperglycemia." (PMID 37445766, 2023). "In Mc4r-KO mice, hepatic FASN deficiency ameliorated hyperglycemia in the fed state." (PMID 37681411, 2023). "However, only male Mc4r knockout mice fed an HF diet, compared with control mice fed an HF diet or Mc4r knockout mice fed an LF diet, exhibit HF diet–induced hyperglycemia." (PMID 30997487, 2019). "DKO also showed more severe glucose intolerance and hyperglycaemia than Mc4r KO." (PMID 27713523, 2016). "Additionally, our Mc4r KO rats have similar body size and hyperglycaemia phenotypic characteristics as Mc4r KO mice." (PMID 27713523, 2016). "The fact that hepatic FASN deficiency exacerbates fed hyperglycemia only on the ob/ob genetic background may be explained by the increased hepatic citrate levels apparent in ob/ob HKO mice but not in Mc4r-KO HKO mice." (PMID 37681411, 2023). "Interestingly, MC3R and MC4R double KO mice and rats displayed even higher levels of adiposity, as well as more severe glucose intolerance and hyperglycemia than their MC4R KO counterparts, which indicated that the functions of the two melanocortin receptors are not mutually redundant." (PMID 31138220, 2019). "Despite the fact that MC3R and MC4R deficiency showed an opposite effect on food consumption and body weight in our mutant rats, we observed additive effects of Mc3r KO to Mc4r KO in phenotypes including adipocyte size, hepatic steatosis, lipid profile, OGTT and hyperglycaemia." (PMID 27713523, 2016). "Only DKO rats showed elevated PBG levels at 7 weeks (n = 8, p = 0.0008), but both Mc4r KO and DKO displayed hyperglycaemia by 13 weeks of age (n = 6, p = 0.02 for Mc4r KO, p = 0.002 for DKO)." (PMID 27713523, 2016). "Unexpectedly, unlike ob/ob HKO mice, Mc4r-KO HKO mice manifested significantly attenuated hyperglycemia in the fed state without exacerbation of liver dysfunction and enhanced expression of related genes in the liver." (PMID 37681411, 2023). "Consistent with the lack of exacerbation of fed hyperglycemia in Mc4r-KO HKO mice, the hepatic citrate level in these mice was identical to that in Mc4r-KO F/F mice." (PMID 37681411, 2023). "While the insulin therapy corrected hyperglycemia in the diabetic mice, it did not restore Pomc or Mc4r expression in ARC or PVH, respectively." (PMID 30503832, 2019). "Hyperglycemia in mothers with GDM is a teratogenic condition that affects organogenesis and induce epigenetic changes primarily through insulin production, modifications Melanocortin 4 receptor, lipoprotein lipase, and leptin methylation patterns, and increased adiposity in the growing fetus." (PMID 40319278, 2025).
Hyperglycemia (continued). "In addition, although the method of glucose measurement in a 52-week treatment protocol was different from that in 8- and 20-week treatment protocols, CANA did not attenuate hyperglycemia in WD-fed MC4R-KO throughout 52-week of WD feeding." (PMID 29402900, 2018).
Anorexia (23 papers, 2009 to 2025). Lack of desire to eat (loss of appetite). "Administration of TCMCB07, a synthetic antagonist of the melanocortin-4 receptor, alleviates chemotherapy-induced anorexia and weight loss." (PMID 39509261, 2024). "Taken together, we present an immunometabolic mechanism of appetite regulation during cachexia in which LCN2 is derived from the bone marrow compartment, crosses the BBB, and binds to the MC4R in mediobasal hypothalamic neurons to mediate long-term anorexia and subsequent loss of lean and fat mass." (PMID 33824339, 2021). "Consistent with LCN2’s proposed MC4R-dependent role in cancer-induced anorexia, pharmacologic MC4R antagonism mitigates cachexia-anorexia, while restoration of Lcn2 expression in the bone marrow is sufficient in restoring the anorexia feature of cachexia." (PMID 33824339, 2021). "The observed effects of SNT207858 and SNT207707 in the C26 cancer cachexia model are in line with previous findings by us and other groups reporting effects of MC4-R antagonism in animals with cancer induced anorexia." (PMID 19295909, 2009). "The difference in food intake between Mc4r KO and WT mice injected with saline may be attributed to the documented enhanced stress-induced anorexia in Mc4r KO mice." (PMID 26829592, 2016). "MC4-R antagonists have also been shown to be effective against cancer-induced anorexia." (PMID 26758700, 2016). "Given the important role of the PVH in mediating melanocortin-induced satiety, and the identification of numerous ARC inputs to IRS4PVH neurons, we hypothesized that IRS4PVH neurons might contain melanocortin 4 receptors (MC4R) and participate in melanocortin agonist-induced anorexia." (PMID 32218485, 2020). "Moreover, MC4Rs expressed on D1R MSNs mediate parts of the phenotype observed in MC4R null mice, such as increased meal size, insensitivity to cocaine-induced anorexia and locomotor sensitization and the inability to be conditioned for high-fat food reinforcers." (PMID 24723856, 2014). "During anorexia, NGAL crosses the blood–brain barrier and binds directly to melanocortin 4 receptor in hypothalamic neurons." (PMID 37893197, 2023). "Acute inflammation activates POMC neurons, which increase melanocortin-4 receptor (MC4R) expression and POMC expression, as shown in the LPS- and IL-1β-induced anorexia model." (PMID 34899611, 2021). "In conclusion, we demonstrated that the initiation of novelty stress-induced anorexia in aged mice is due to 5-HT2CR and CRFR1/MC4R activation." (PMID 27273195, 2016). "In rodent kidney disease, it has been shown that MC4R and POMC play a role in anorexia, modifying body composition, and this involves cytokines." (PMID 26734008, 2015). "DON-induced anorexia can indirectly affect appetite by inducing a significant release of peripheral satiety hormones, in addition to upregulating central anorexigenic molecules such as POMC and melanocortin 4 receptor (MC4R)." (PMID 39691381, 2024). "Given that anorexia in this model is reversible with melanocortin antagonists, this lends further support to the idea that normal homeostatic melanocortin signaling is bypassed by LCN2 acting as an MC4R agonist under pathological conditions." (PMID 35031523, 2022). "Consistent with this, mice lacking the MC4R resist IL-1β induced anorexia, demonstrating that alterations in melanocortin signaling underlie changes in feeding in response to IL-1β." (PMID 23031643, 2012). "Melanocortin 4 receptor antagonists are very effective in reversing different types of anorectic conditions in animal models, for example, selective melanocortin MC4 receptor blockage reduces immobilization stress-induced anorexia in rats." (PMID 22770364, 2012).
depression (23 papers, 2016 to 2025). "This study investigates the interactions between the MC4R gene variant (rs17782313) and dietary patterns on depression among Iranian obese and overweight women." (PMID 37072742, 2023). "For instance, MC4R rs17782313 was associated with anthropometric (body weight, p = 0.003; BMI, p = 0.001; body fat percentage, p = 0.014) and psychological measures (depression; p = 0.048) at baseline." (PMID 38062157, 2023). "Using the Generalized linear Model (GLM), the interaction between MC4R polymorphism (rs17782313) and dietary patterns on depression was examined." (PMID 37072742, 2023). "Indeed, the cross-sectional design precludes causal inferences into the interaction between dietary intake and depression in individuals at risk for the MC4R gene allele." (PMID 37072742, 2023). "Based on the findings of the study, we found that there was a positive relationship between increased adherence to CSI and depression in TC allele carriers of MC4R, and there was also a positive relationship between higher N6/N3 ratio and depression in AG-allele carriers of CAV1." (PMID 37311812, 2023). "Some animal evidence via the hypothalamicpituitary‐adrenal (HPA) axis have shown the relationship between MC4R and mental stress and depression and food intake." (PMID 37311812, 2023). "The findings of this study show that the interaction of MC4R variants between individuals and high consumption of UDP can play an important role in the development of depression." (PMID 37072742, 2023). "Our findings showed that a positive interaction between TC allele carriers of MC4R and higher adherence of CSI on depression and DASS-21." (PMID 37311812, 2023). "The aim of this study was to determine the relationship between dominant dietary patterns and MC4R with depression in overweight and obese Iranian adults." (PMID 37072742, 2023). "Three melanocortin receptor genes (MC1R, MC2R, and MC5R) contribute to the risk of major depressive disorder (MDD), and one melanocortin receptor gene (MC4R) contributes to the risk of type 2 diabetes (T2D)." (PMID 35955479, 2022). "Moreover, the authors also noted that rs17782313 was significantly associated with depression and overeating behaviors, and that MC4R leads to weight gain and BMI via depression and overeating behaviors." (PMID 37072742, 2023). "Moreover, MC4R rs17782313, by the restriction fragment length polymorphism (PCR-RFLP) method, and depression, using the 21-item Depression Anxiety Stress Scales (DASS) questionnaire, were assessed." (PMID 37072742, 2023). "According to a contemporary approach to nutrition epidemiology, where the role of mediators between diet and genes is considered, we, for the first time in Iran and the world, discerned the interaction between the dominant food intake pattern and MC4R 17782313rs on mood disorders (depression)." (PMID 37072742, 2023). "This may be because most people in the study chose an UDP as their dominant diet, and therefore, the interaction between the MC4R gene and an UDP is more closely linked to depression." (PMID 37072742, 2023). "In general, studies on the effect of the MC4R gene and depression are very limited." (PMID 37072742, 2023). "However, there was a significant difference between depression and stress and MC4R rs17782313 genotypes in all study groups (p ˂0.05)." (PMID 36123585, 2022). "The expression level of the 5-HT1A, DRD1, ADRA-2A, GABA-A α1, CNR1, NR3C2, NOD1, NLRP3 and MC4R; BDNF levels, glial activity and intestinal permeability were determined in chronic stress-induced depression in rats." (PMID 40281288, 2025). "In the crude model, a positive interaction was observed between TC genotype of MC4R and CSI on depression (β = 0.30, CI = 0.04, 0.56, P = 0.023), and DASS-21 (β = 0.62, CI = − 0.32, 1.27, P = 0.062)." (PMID 37311812, 2023).
depression (continued). "After adjusting for age, energy intake, thyroid disease, physical activity, and BMI in model 1, the interaction between TC genotype of MC4R and CSI on depression (β = 0.39, CI = 0.12, 0.66, P = 0.004), and DASS-21 (β = 0.074, CI = 0.04, 1.44, P = 0.036) remained positive." (PMID 37311812, 2023). "The results of the study showed that after adjusting for age, energy intake, thyroid disease, physical activity, and BMI, a positive interaction between TC genotype of MC4R and CSI on depression (β = 0.39, CI = 0.12, 0.66, P = 0.004), and DASS-21 (β = 0.074, CI = 0.04, 1.44, P = 0.036)." (PMID 37311812, 2023). "In our study, the MC4R variant rs571312(and others, but not FTO) was identified as an influential (and potentiallyinvalid) instrument in major depressive disorder analysis, but not in the remainingoutcomes." (PMID 27601421, 2016).
Bardet-Biedl syndrome (22 papers, 2019 to 2025). A ciliopathy with multisystem involvement. "A phase 2 trial has suggested that treatment with the melanocortin-4 receptor (MC4R) agonist setmelanotide is associated with a decrease in hunger and weight-related outcomes in participants with Bardet-Biedl syndrome (BBS) and Alström syndrome." (PMID 34013094, 2021). "There are no validated measures to assess hyperphagia associated with rare MC4R pathway diseases, such as Bardet-Biedl Syndrome (BBS)." (PMID 40847358, 2025). "POMC, PCSK1, and LEPR deficiencies and Bardet-Biedl syndrome (BBS) can be counter-regulated by the MC4R agonist setmelanotide." (PMID 40822950, 2025). "Similar clinical features are also observed in patients suffering from HO syndrome due to a genetic abnormality (i.e. melanocortin-4 receptor defect, leptin or proopiomelanocortin (POMC) deficiency, Bardet-Biedl Syndrome)." (PMID 37780616, 2023). "On the contrary, some genetic obesity disorders related to the impairment of MC4R signalling (i.e., Bardet–Biedl syndrome) characterised by significant hyperphagia showed an excellent response to setmelanotide, a selective agonist of MC4R." (PMID 37508552, 2023). "Setmelanotide (or RM-493) is an agonist of the appetite-regulating melanocortin-4 receptor which is being investigated for different forms of genetic obesity, including Bardet-Biedl syndrome." (PMID 34640558, 2021). "Variants in genes involved in these pathways can result in Bardet-Biedl syndrome (BBS) and Alström syndrome, rare genetic diseases associated with impaired ciliary function and insufficient MC4R signaling." (PMID 34013094, 2021). "Informed by these mechanistic studies, successful phase 3 clinical trials have led to a second generation MC4R agonist being licensed in many countries for the treatment of several monogenic disorders (POMC, PCSK1, LEPR deficiencies and Bardet-Biedl Syndrome (BBS))." (PMID 37661743, 2023). "Additionally, the patient had genetically supported Bardet-Biedl Syndrome (BBS), providing a well-defined disease context in which to assess the effects of melanocortin-4 receptor (MC4R) agonism." (PMID 41333852, 2025). "Although multiple melanocortin receptor agonists have been investigated, setmelanotide is currently the only MC4R agonist approved by the FDA for the treatment of specific genetic forms of obesity, including deficiencies in POMC, PCSK1, and LepR, as well as Bardet-Biedl syndrome (BBS)." (PMID 41016636, 2025).